RAP1B (RAP1B, member of RAS oncogene family)
Diseases named in the same sentence as RAP1B in open-access papers (continued):
Sharing a sentence is not in itself a finding about the gene and the disease.
tumor (continued). "The miR-708 expression was significantly decreased in tumour samples, while expression of Rap1B was increased, suggesting an inverse correlation between Rap1B and miR-708 expression." (PMID 25569036, 2015). "Moreover, the silencing of circPHGDH inhibited tumor growth and metastasis in vivo via the miR-149/RAP1B axis, whereas circPHGDH facilitated tumor progression." (PMID 41760734, 2026). "Concurrently, loss of Rap1B enhances CD8+ T-cell infiltration, suggesting that targeting Rap1B could represent a novel strategy to overcome tumor immune suppression." (PMID 41050070, 2025). "Targeting Rap1B in the tumor microenvironment may enhance immune cell infiltration and disrupt vascular immunosuppression while preserving normal endothelial function by avoiding systemic inhibition." (PMID 40508181, 2025). "Recent studies have shown that RAP1B was involved in multiple tumours progression." (PMID 40638546, 2025). "Moreover, FN1 and RAP1B were also positively upregulated in PTCs from primary and metastatic colon cancer tumour tissues." (PMID 40638546, 2025). "In a pathological tumor microenvironment, Rap1B promotes both angiogenesis and immune evasion." (PMID 40508181, 2025). "Selective inhibition of Rap1B may sensitize tumor endothelium to inflammatory cues and enhance immune cell infiltration but must be carefully balanced to preserve its physiological roles." (PMID 40508181, 2025). "These mechanistic insights, combined with mouse models and human transcriptomic analyses, highlight the differential physiological roles of Rap1A and Rap1B and their implications for vascular pathologies, including inflammation, tumor angiogenesis, and endothelial dysfunction." (PMID 40508181, 2025). "This raises the possibility that EC Rap1B contributes to tumor growth." (PMID 39337337, 2024). "In vivo, Rap1B deficiency results in impaired neonatal retinal angiogenesis, which is dependent on VEGF-A, as well as reduced VEGF-induced Matrigel plug neovascularization, a model of tumor angiogenesis." (PMID 39337337, 2024). "Interestingly, when CD8+ T cells are depleted, tumor growth is normalized in Rap1BiΔEC mice, indicating that Rap1B in tumor ECs plays a crucial role in controlling CD8+ T cell activity." (PMID 39337337, 2024). "In a BLAST search for downstream genes complementary to the SNORA70E sequence, we found that there may be binding sites between SNORA70E and RAP1B, which functions as a tumour promoter." (PMID 36056690, 2022). "Furthermore, the silencing of Rap1b and Nrf2 remarkably repressed the tumor cell infiltration capacity in the common group in contrast with the other groups, especially in the negative control group." (PMID 35417854, 2022). "Current data suggest that RAP1B is overexpressed in many tumours." (PMID 36333693, 2022). "Furthermore, we showed that IL6, CASP3, ACTB, ACTG1 and RAP1B are hub genes that regulate the tumour metastasis regulation network." (PMID 33759378, 2021). "These correlations may be the potential reasons for the positive correlation between the high expression of Rap1b and the poor prognosis in tumor patients, which suggested that Rap1b could be serve as a prognostic biomarker in various tumors." (PMID 34346294, 2021). "Further studies have confirmed that Rap1b is closely related to tumor differentiation, supporting the conclusion that Rap1b may have an oncogene function in the development of NSCLC." (PMID 34178945, 2021). "OSeac could also be used to screen novel prognosis biomarker for EAC, for example, RAP1B contributes to tumor malignant behavior and poor prognosis in GC." (PMID 32211334, 2020). "It has been proposed that miR-518b may function as a tumor suppressor by targeting Rap1b, since Rap1b expression is negatively regulated by miR-518b." (PMID 28182660, 2017). "To further clarify whether the tumor suppression roles of miR-28-5p were dependent on RAP1B expression, we performed a series of functional restoration assays in A498 and ACHN cells." (PMID 27729617, 2016).
tumor (continued). "The Rap1B level in primary tumours was significantly increased in patients with advanced stages of this disease (III/IV) or harbouring metastasis, as compared with normal ovary tissues or early-stage tumours (I/II), and this pattern was opposite to that of miR-708." (PMID 25569036, 2015). "Therefore, targeting Rap1B signaling in tumor ECs could offer a promising strategy to counteract EC anergy in cancer therapy." (PMID 39337337, 2024). "Therefore, it is reasonable to surmise that Rap1b plays an important role in mismatch repair and DNA methylation in pan-cancer and further studies focus on Rap1b expression and tumor immunity could help provide new methods of immunotherapy." (PMID 34346294, 2021). "Therefore, we speculate the effect of Rap1b on the progression of various tumors was related to tumor immune infiltration." (PMID 34346294, 2021). "Firstly, the results suggested that the expression level of Rap1b was related to prognosis and immune infiltration in pan-cancer, we still had no direct evidences to confirm Rap1b affected the prognosis of tumors via acting on immune checkpoints or tumor mutations." (PMID 34346294, 2021). "However, the potential roles and mechanisms of Rap1b in tumor progression and immunology remains unclear." (PMID 34346294, 2021). "Finally, we explored the role of LINC00514 mediated by Rap1b in promoting tumor growth." (PMID 32771045, 2020). "(Section 3.1.1), endothelial deletion of Rap1B leads to inflammatory derepression, enhancing CD45+ and CD8+ T-cell infiltration and activation in tumors, contributing to immune-mediated tumor regression—an effect reversed by CD8+ T-cell depletion." (PMID 40508181, 2025). "Re-expression of miR-708 led to the downregulation of several oncogenic targets including Rap1B, IKKβ, and CD44, all of which contribute to tumor proliferation, invasion, and stemness." (PMID 41008798, 2025). "Lastly, five genes including GSKIP, SELENOF, RAP1B, UBE2D3, and GTF2B, were found to be co-expressed in both adjacent healthy tissue and tumor tissue." (PMID 37365287, 2023). "Ras-related Protein Rap1b, a GTP-binding protein belonging to the proximal RAS, which affects tumor progression through regulating tumor cell proliferation, invasion and participates in the functions of various immune cells." (PMID 34346294, 2021). "Furthermore, Rap1b gene may be used as a potential biomarker of clinical tumor prognosis." (PMID 34346294, 2021). "As a tumor suppressor in RCC, miR-28-5p exerts multiple antitumor effects by directly inhibiting RAP1B." (PMID 34123589, 2021). "Consistently, the number of lung metastasis tumours was significantly elevated in the FN1‐overexpressing group compared with the control group, which was partially restored by the FN1‐overexpressing and RAP1B‐silenced groups." (PMID 40638546, 2025). "In this model, we used EC-specific Rap1B knockout (Rap1BiΔEC) mice and found that the absence of EC Rap1B led to a significant reduction in tumor growth." (PMID 39337337, 2024). "Our studies using EC-specific Rap1B knockout mice show that the absence of Rap1B impairs tumor growth, alters vessel morphology, and increases CD8+ T cell infiltration and activation." (PMID 39337337, 2024). "We performed multivariate Cox regression analysis and differential analysis of gene expression between the tumour and precancerous tissue on 11 prognostic Ras-related genes, and we got three differently expressed prognostic Ras-related genes (EGFR, RAP1B and PDGFRA)." (PMID 35281814, 2022). "Medium or high expression of IL6, CASP3, ACTB and RAP1B was observed in 14/20 (~70%) lung metastasis tissues and in 11/20 (~55%) tumour tissues, whereas the expression was negative in the majority of adjacent non‐tumour tissues." (PMID 33759378, 2021).
tumor (continued). "Indeed, both MAPK1 and RAP1B, a Ras-related small GTP-binding protein that acts as GTPase in several signaling cascades, are proproliferative proteins involved as oncogenes in the development and progression of several tumor types." (PMID 29085832, 2017). "When we examine the expression of Rap1B in ECs from tumors in lung, colorectal, and ovarian cancer patients using publicly available single-cell RNA sequencing (scRNAseq) data, we find that its levels are notably higher in tumor ECs compared to their non-tumor counterparts." (PMID 39337337, 2024).
cancer (29 papers, 2012 to 2025). A tumor composed of atypical neoplastic, often pleomorphic cells that invade other tissues. "Among the enriched targets that are more strongly associated with cancer (i.e., RAP1B, N4BP1, MAPK1, and E2F6), almost all are protumoral." (PMID 29085832, 2017). "In summary, Rap1—particularly Rap1B—emerges as a context-dependent mediator of pathological angiogenesis and immune evasion in cancer and other vascular diseases." (PMID 40508181, 2025). "KEGG enrichment showed that FN1 related genes were mainly enriched in RAP1 and RAS signalling pathway, in which Ras‐related protein RAP1B was involved and played key roles in cancer metastasis." (PMID 40638546, 2025). "Targeting Rap1B offers a novel strategy to overcome EC anergy and improve cancer treatment outcomes." (PMID 39337337, 2024). "Endothelial Rap1B is emerging as a key player in cancer progression, as suggested by several findings." (PMID 39337337, 2024). "Excessive RAP1B promotes cancer cell development, elevates p38 MAPK phosphorylation levels, and reverses the effects of si-DLEU2 on OC cells." (PMID 36277988, 2022). "Accumulating data indicate that the deregulated activation of RAP1B is related to a series of malignant tumors, and that RAP1B has effects on cell proliferation, metastasis, angiogenesis, and treatment resistance." (PMID 33676540, 2021). "So far, there is no crystal structure of the human GGTase-I in complex with its substrate Rap1B available, and understanding the key features of substrate specificity will contribute to optimization of anti-cancer drugs." (PMID 33801503, 2021). "Rap1b expression was higher in cancer groups compared with the respective normal groups, including bladder, brain, cervical, esophageal, gastric, head, and neck, kidney, pancreatic and sarcoma cancer." (PMID 34346294, 2021). "In summary, Rap1b expression was correlated with prognosis in 10 types of cancer, especially in KICH, LIHC, PAAD, MESO, and with increased immune infiltration levels of B cells, CD4 + T cells, CD8 + T cells, neutrophils, dendritic cells in various cancers." (PMID 34346294, 2021). "Many studies have indicated that Rap1B is required for cell survival and migration in human cancer cell models and is targeted by several miRNAs." (PMID 33801503, 2021). "In the data of 32 cancers, the expression of Rap1b in 8 cancers was significantly correlated with TMB, including THCA, BRCA, LGG, READ, LIHC, PRAD, COAD, UVM." (PMID 34346294, 2021). "The expression of TLN1 and TLN2 was positively associated with CNV in most cancers, except for APBB1IP, RAP1B, and RAP1A." (PMID 33391455, 2021). "In this study, we systematically analyzed the pan-cancer expression and prognostic correlation of Rap1b based on GTEX, CCLE, Oncomine, PrognoScan, Kaplan–Meier plotters and TCGA databases." (PMID 34346294, 2021). "In the analysis of the correlation between DSS and Rap1b expression in different cancers, 8 cancer types showed the significant relationship." (PMID 34346294, 2021). "The finding that Rap1B prenylation is reduced in rat mammary tumors provides additional evidence that this pathway has a role in cancer." (PMID 34222337, 2021). "A2bR activation inhibits isopentenization of GTPase Rap1B (Guanine 5′‐triphosphate Ras‐proximate‐1), leading to decreased intercellular adhesion mediated by Rap1B and promoting metastasis of cancer cells." (PMID 32875727, 2020). "Rap1b, acting as a cancer-promoting gene, had a positive correlation with LINC00514, while there was a negative relationship between Rap1b and miR-28-5p." (PMID 32771045, 2020). "Nonetheless, exosomal proteins previously reported to be associated with vesicle secretion in cancer cell line supernatants (RAP1A, RAP1B, VAMP1, MYH7, MYO18a, MYOLPF, MYO1E, VPS13B, HSP70) were identified in our samples." (PMID 30764491, 2019).
cancer (continued). "MicroRNA-708 has been reported to suppress cell progression and metastasis in certain cancer types by inhibiting different targets, namely Rap1B, neuronatin, or survivin." (PMID 28591224, 2017). "Beyond cancer, Rap1B plays a protective role in cardiovascular disease." (PMID 40508181, 2025). "Additionally, cancer disease pathways showed 37 proteins at high levels, including integrin beta-3, integrin alpha-IIb, vinculin, actin, cytoplasmic 1, Ras-related protein Rap-1b, and talin-1." (PMID 40564899, 2025). "One emerging target for anti-angiogenic therapy in cancer is the small GTPase Rap1B." (PMID 39337337, 2024). "Furthermore, RAP1B expression is correlated with the immune infiltration of tumors in various cancers." (PMID 37663388, 2023). "Other studies indicate that the regulatory functions of individual C19MC miRNAs in cancer are related to silencing the expression of factors and signaling pathways related to adhesion, migration, differentiation, growth and angiogenesis (Rap1b, ABCG2, DAPK2, ephrins-EphB2 and EphB4, CXCR4)." (PMID 36430313, 2022). "RAP1B has been reported to have a positive effect on the progression of some types of cancer." (PMID 35632705, 2022). "In addition, Rap1b had been reported to be involved in the development and progression of a variety of malignant tumors." (PMID 34346294, 2021). "Reduced Rap1B prenylation was detected in different cancer cell lines and tumors." (PMID 33801503, 2021). "In addition, the roles of Rap1b in immunology in pan-cancer has seldomly been analyzed systematically." (PMID 34346294, 2021). "Rap1b was also found to participate in cell migration and invasion in cancer cells." (PMID 29599749, 2018). "Thus, A2AAR and A2BAR antagonists might be promising candidates for therapeutic intervention for different types of cancer that overexpress Rap1B." (PMID 33801503, 2021). "However, human pan-cancer evidences regarding the potential function of Rap1b in various tumors remains unclear." (PMID 34346294, 2021). "In addition, Rap1b expression had significant correlation with infiltrating levels of B cells in 21 types of cancer, CD4 + T cells in 18 types of cancer, CD8 + T cells in 24 types of cancer, neutrophil in 27 types of cancer, macrophage in 26 types of cancer and dendritic in 26 types of cancer." (PMID 34346294, 2021). "Furthermore, the pan-cancer expression of Rap1b was examined by Oncomine and TIMER2 database." (PMID 34346294, 2021). "Therefore, we further analyzed whether the differential expression level of Rap1b was related to the prognosis of cancer patients." (PMID 34346294, 2021). "This indicates that Rap1B mediates VEGF-A’s immunosuppressive effects, making it a promising target for overcoming vascular immunosuppression in cancer." (PMID 39337337, 2024). "Overall, in three types of cancer (BRCA, COAD, and KIRC), Rap1b expression showed the most relevant to immune infiltration levels." (PMID 34346294, 2021). "Therefore, Rap1b may be used as a novel anticancer immunotherapy drug target or in combination with known immune checkpoint inhibitors to enhance immune and responses in cancers." (PMID 34346294, 2021). "Regarding the model that increased Rap1B geranylgeranylation and thereby increased cell adhesion decreases metastasis, A2AAR and A2BAR antagonists are promising candidates for therapeutic intervention in different types of cancer that overexpress Rap1B." (PMID 33801503, 2021). "Hence, we calculated the TMB and MSI of each sample in all tumors and explored the relationship between Rap1b expression, TMB and MSI in different cancer types using Spearman rank correlation test." (PMID 34346294, 2021). "Thus, we suggest that SNORA70E might regulate RAP1B and further regulates the expression of β‐catenin, PI3K, AKT1, mTOR, and MMP9 to exert cancer‐promoting effects." (PMID 36056690, 2022).
cancer (continued). "We found that Rap1b expression had significant correlation with infiltrating levels of B cells in 21 types of cancer, CD4 + T cells in 18 types of cancer, CD8 + T cells in 24 types of cancer, neutrophil in 27 types of cancer, macrophage in 26 types of cancer and dendritic in 26 types of cancer." (PMID 34346294, 2021). "In this study, we systematically analyzed the expression level of Rap1b and its prognostic correlations, using Genotype-Tissue Expression (GTEx), Cancer Cell Line Encyclopedia (CCLE), Oncomine, PrognoScan, Kaplan–Meier plotters and The Cancer Genome Atlas (TCGA) databases." (PMID 34346294, 2021).